CREB3L2 (cAMP responsive element binding protein 3 like 2)
Diseases named in the same sentence as CREB3L2 in open-access papers:
CREB3L2 is named in the same sentence as 47 diseases in open-access papers, as found by Europe PMC text mining. Sharing a sentence is not in itself a finding about the gene and the disease. The quoted sentences say what the papers report.
prostate carcinoma (7 papers, 2010 to 2025). A carcinoma that arises from epithelial cells of the prostate gland. "Concerning CREB3L2, it collaborates with the androgen receptor to regulate the ER-to-Golgi trafficking pathway to drive prostate cancer progression." (PMID 39337607, 2024). "Androgen receptor activates CREB3L2, increasing protein trafficking in prostate cancers, but the biochemical details remain to be elucidated." (PMID 36313580, 2022). "The -7q32.3q34 MCR contained the CREB3L2 gene, a transcription regulator involved in prostate cancer." (PMID 22253721, 2012). "Notably, BRAF and CREB3L2 are both in the KEGG pathway for prostate cancer, thus raising the possibility that PLX4720 may also play a role in interfering with CREB3L2 binding to DNA and impacting transcription, possibly in prostate cancer." (PMID 26132924, 2015).
sarcoma (6 papers, 2011 to 2020). A usually aggressive malignant neoplasm of the soft tissue or bone. "Increased expression of UBE2C, CENPE and CREB3L2 compared to normal muscle was detected in 9 of 9 human sarcoma cell lines analyzed, whereas HAS2 expression was detected in only 5 of 9 human sarcoma lines." (PMID 32898143, 2020). "Given that downregulation of Ube2c, Cenpe, Has2 and Creb3l2 by shRNA knockdown diminished mouse sarcoma cell proliferation in vitro, we hypothesized that small molecule inhibitors previously reported to impede the cellular functions of these targets could prove useful in inhibiting their growth." (PMID 32898143, 2020). "As prior work already has validated asparagine starvation as an actionable metabolic vulnerability in sarcomas, this study concentrates on the potential roles of UBE2C, CENPE, HAS2 and CREB3L2 in STS with a focus on RMS." (PMID 32898143, 2020). "Translocation of CREB3L2 gene, located on chromosome 7, and the FUS gene (fused in sarcoma) located on the chromosome 16 has been found in some tumors, including skin cancer and soft tissue sarcoma." (PMID 30940212, 2019).
breast carcinoma (3 papers, 2015 to 2022). "After screening, source genes closely associated with canine mammary tumours were found to include RYR2, PDE4D, ROCK2, CREB3L2 and UBA3, and associated circRNAs included chr27:26618544-26687235-, chr26:8194880-8201833+ and chr17:7960861-7967766-." (PMID 35622733, 2022).
malignant glioma (3 papers, 2011 to 2022). A grade III or grade IV glioma arising from the central nervous system. "Taken together, these findings revealed an antiapoptotic activity of CREB3L2 and provided a new mechanism to explain the uncontrolled proliferation of malignant glioma cells." (PMID 21711675, 2011). "Finally, a recent RNAi screen revealed a role for CREB3L2 in the survival pathway in malignant glioma cells." (PMID 21711675, 2011). "It was also described that, in malignant glioma, an FRS2/PAK1-activated RAS/MAPK signaling cascade up-regulates CREB3L2, which directly binds to the ATF5 promoter resulting in ATF5 transcription, an anti-apoptotic factor which plays a role in cell survival." (PMID 31334233, 2019). "The TF, CREB3L2, found in TR NFO has been found to take part in malignant glioma survival pathway." (PMID 34976314, 2022).
thyroid cancer (3 papers, 2011 to 2025). "It is reported that CREB3L2 protein can be hydrolyzed by intramembrane proteins to produce cytosolic CREB3L2, which promotes thyroid carcinoma cell proliferation and inhibits camp response transcription." (PMID 41285809, 2025). "In further support of the oncogenic property of CREB3L2, it was also found to be involved in another chromosomal translocation in thyroid carcinoma that gives rise to the CREB3L2-PPARγ fusion oncogene." (PMID 21711675, 2011). "The endocrine function of the thyroid gland prompted us to the hypothesis that CREB3L2-PPARγ might also exert an impact on protein secretion in thyroid carcinoma." (PMID 21711675, 2011).
Alzheimer disease (2 papers, 2023 to 2025). A progressive, neurodegenerative disease characterized by loss of function and death of nerve cells in several areas of the brain leading to loss of cognitive function such as memory and language. "Alzheimer’s disease (AD) pathology includes transcriptional changes in the neurons, which are in part caused by the heterodimerization of two stress response transcription factors, CREB3L2 and ATF4." (PMID 40164587, 2025).
brain ischemia (2 papers, 2019 to 2022). Diminished or absent blood supply to the brain caused by obstruction (thrombosis or embolism) of an artery resulting in neurologic damage. "Upregulation of Creb3l1 was found proximal to the injury site, and Creb3l2 was also found in the peri-infarction region in a brain ischemia mouse model to restore the injury region." (PMID 35469040, 2022). "Expression of CREB3L2 in vivo was analyzed by immunohistochemistry in a mouse model of permanent focal brain ischemia where CREB3L2 was detected in the region closer to the infarction region in the striatum, especially in neurons (labeled with MAP2)." (PMID 31334233, 2019).
glioblastoma (2 papers, 2015 to 2016). The most malignant astrocytic tumor (WHO grade IV). "ATF5 is highly expressed in primary brain tumors, especially in glioblastoma, and plays a key role in promoting cancer cell survival through the CREB3L2/ATF5/MCL1 pathway." (PMID 27023521, 2016).
glioma (2 papers, 2016 to 2020). A benign or malignant brain and spinal cord tumor that arises from glial cells (astrocytes, oligodendrocytes, ependymal cells). "Latrunculin A was previously shown to reduce HAS2 expression in fibroblasts, and sorafenib was shown to reduce CREB3L2 expression in glioma cells." (PMID 32898143, 2020). "Three genes RND3, OSRM, and CREB3L2 were focused, for their closely relation to glioma." (PMID 27023521, 2016). "Three genes closely related to glioma, RND3, OSMR, and CREB3L2, were significantly upregulated and might be the key factors in EBLN1 regulating the proliferation and apoptosis of OL cells." (PMID 27023521, 2016).
myeloma (2 papers, 2020 to 2025). "Consequently, these innovations establish a novel conceptual framework for understanding how transcriptional regulators such as CREB3L2 dynamically repress angiogenesis during myeloma progression—insights that were not addressed by existing single-cell endothelial atlases." (PMID 40636123, 2025).
soft tissue sarcoma (2 papers, 2019 to 2025). A malignant neoplasm arising from muscle tissue, adipose tissue, blood vessels, fibrous tissue, or other supportive tissues excluding the bones. "We hypothesize that this distinctive morphology and molecular phenotype may be linked to the high-grade transformation (HGT) process of low-grade malignant soft tissue sarcoma, where tumor development is driven by the FUS:: CREB3L2 fusion, leading to dedifferentiation into a pure SEF form." (PMID 40144208, 2025).
alcoholism (1 paper, 2022). "Interestingly, the GO term “alcoholism” was enriched in genes associated with the “CGI-free intergenic UMR” category, including Shc3, Shc4, Araf, Fosb, Hdac11, Adcy5, Creb3l2, Gnai2, Grin2d, and Ppp1r1b." (PMID 35205351, 2022).
leiomyosarcoma (1 paper, 2020). An uncommon, aggressive malignant smooth muscle neoplasm, usually occurring in post-menopausal women. "In human leiomyosarcomas (LMS), expression of UBE2C was found in 12 of 26 (46%), of CENPE in 7 of 26 (27%), of HAS2 in 7 of 26 (25%) and of CREB3L2 in 20 of 27 (74%) human leiomyosarcoma cores." (PMID 32898143, 2020).
liver fibrosis (1 paper, 2021). "In contrast, miR-92b can promote the progression of liver fibrosis by activating JAK/STAT pathway via targeting CREB3L2 and limiting the production of intermediate cortical progenitors." (PMID 34829725, 2021).
neuroblastoma (1 paper, 2017). Neuroblastoma (NB) is the most common solid, extracranial childhood tumor. "Remarkably, it has been demonstrated that CREB3L2, whose expression is induced by endoplasmic reticulum (ER) stress, is involved in preventing the accumulation of unfolded proteins in normal damaged neurons, and protecting neuroblastoma cells from ER-stress induced cell death." (PMID 29020091, 2017).
papillary thyroid carcinoma (1 paper, 2025). "Cytopathologic diagnosis was suspicious for papillary thyroid carcinoma and ThyroSeq molecular testing revealed an underlying CREB3L2::PPARγ fusion, implying a high risk for “malignancy or non-invasive follicular thyroid neoplasm with papillary-like nuclear features (NIFTP)”." (PMID 40839045, 2025).
pituitary tumor (1 paper, 2020). A benign or malignant neoplasm affecting the pituitary gland. "To this end, we analyzed an RNA-seq dataset involving overexpression (OE) of active forms of XBP1 (spliced form) and Creb3l2 (cleaved form) in the mouse pituitary tumor cell line AtT-2045." (PMID 32576858, 2020).
Sepsis (1 paper, 2025). Sepsis is defined as life-threatening organ dysfunction caused by a dysregulated host response to infection. "In addition, the present study demonstrated that both CREB3L2 and BCL2L1 were upregulated and were identified as positively correlated with one another as well as with the sepsis score." (PMID 40867920, 2025). "Furthermore, a positive correlation was observed between cAMP responsive element binding protein 3 like 2 (CREB3L2) and BCL2L1, as well as between the expressions of USP14 and YOD1 deubiquitinase (YOD1) in sepsis." (PMID 40867920, 2025).
tumor (14 papers, 2011 to 2025). "Notably, high expression of the transcription factor cAMP-responsive element-binding protein 3-like 2 (CREB3L2) in the C1 subgroup was associated with the inhibition of angiogenesis and tumor cell proliferation and migration." (PMID 40636123, 2025). "Consistent with our previous experimental findings, the CREB3L2 level exhibited a significant increase in tumor tissues compared to the paired peritumoral tissues." (PMID 41285809, 2025). "A total of 75 genes, including TARGET genes (importance > 10) related to the specific transcription factor CREB3L2 of C1 tumor cells and angiogenesis genes, were used for univariate Cox analysis to screen out genes related to survival." (PMID 40636123, 2025). "Transwell migration and matrix gel invasion assays demonstrated that suppression of CREB3L2 reduced cell migration and invasion, ultimately restoring the anti-tumor effects of lenvatinib in vitro." (PMID 41285809, 2025). "CREB3L2, involved in the unfolded protein response, likely contributes to tumor survival under stress, enabling cancer cells to adapt to challenging microenvironments." (PMID 39851951, 2025). "In contrast to the control group, the knockdown of CREB3L2 elicited a marked deceleration of the tumor growth rate and a substantial reduction in tumor weight." (PMID 41285809, 2025). "To determine the expression pattern of CREB3L2 in human malignancies, we conducted a comparison of mRNA levels across 23 different tumor types using data from TCGA database." (PMID 41285809, 2025). "Immunohistochemical staining demonstrated that within the tumor tissues showing CREB3L2 overexpression, the expressions of SREBP1 and fatty acid-synthesizing enzymes were elevated correspondingly, which is consistent with our in vitro results." (PMID 41285809, 2025). "Subsequently, downregulation of CREB3L2 reduced lung metastatic lesions and greatly attenuated lenvatinib resistance to tumor metastasis." (PMID 41285809, 2025). "In summary, knocking down CREB3L2 can play an anti-tumor role by promoting apoptosis, inhibiting EMT, and cell migration and invasion." (PMID 40636123, 2025). "Within the specifically selected HCC cell lines, the colony formation assay demonstrated that alterations in the expression level of CREB3L2 exerted a noteworthy impact on the proliferative capacity of tumor cells." (PMID 41285809, 2025). "Consistent with expectations, within the tumor xenograft model of 97H cells subjected to shCREB3L2 treatment, it was observed that the knockdown of CREB3L2 substantially inhibited tumor growth and reinstated the anti-tumor effectiveness of lenvatinib." (PMID 41285809, 2025). "In both in vitro and in vivo experiments, we demonstrated that the CREB3L2/HAT1/SREBP1 axis promotes tumor cell proliferation and metastasis by enhancing lipid metabolism, and targeting CREB3L2 can partially overcome lenvatinib resistance to augment therapeutic efficacy." (PMID 41285809, 2025). "Additionally, the subcutaneous xenograft model demonstrated that inhibiting SREBP1 significantly suppressed tumor growth driven by CREB3L2 overexpression." (PMID 41285809, 2025). "Further, we used subcutaneous tumor and tail vein metastasis models in nude mice to assess whether CREB3L2 has the same role in vivo." (PMID 41285809, 2025). "Remarkably, the combined Creb3l2 plus XBP1 expression in the tumor-derived AtT-20 cells led to a shift of energy metabolism from glycolysis to oxidative phosphorylation, resulting in more efficient ATP production and providing for support of heavy protein synthesis." (PMID 31481663, 2019). "Conversely, an elevation in the expression level of CREB3L2 was accompanied by a concomitant increase in both the tumor growth rate and tumor dimensions, with corresponding changes in the number of lung metastatic nodules in mice based on the knockdown or overexpression of CREB3L2." (PMID 41285809, 2025).
tumor (continued). "In addition, higher CREB3L2 levels were significantly associated with tumor stage progression in patients, but not with other indicators such as patient age, gender, tumor size, etc." (PMID 41285809, 2025). "Other pathways, such as Ras (RAF1, RALBP1, RASSF1), TGF-β (CREB3L2/3, CREB5, TCL1A), Rap1, Hippo, and axonal guidance, further facilitate tumour migration and spread." (PMID 41007296, 2025). "Despite lenvatinib’s partial inhibition of SREBP1 expression, it fails to efficiently suppress the tumor progression in HCC owing to the comparatively high expression level of CREB3L2." (PMID 41285809, 2025). "Our findings indicate that CREB3L2 can enhance lipogenesis in HCC cells by up-regulating the key enzyme involved in fatty acid synthesis, which energizes the malignant proliferation and metastasis of tumor cells." (PMID 41285809, 2025). "Considering the crucial part that lipid metabolism plays in tumor progression, we performed rescue experiments to assess whether SREBP1 is involved in CREB3L2-mediated malignant biological behavior of HCC cells." (PMID 41285809, 2025). "We further examined the clinical relevance of CREB3L2 expression by analyzing three separate HCC patient dataset from the GEO, the results also verify that the expression of CREB3L2 is sustainedly markedly upregulated in HCC tumor samples compared to adjacent non-tumor tissues." (PMID 41285809, 2025).
cancer (13 papers, 2010 to 2025). A tumor composed of atypical neoplastic, often pleomorphic cells that invade other tissues. "On the other hand, CREB3L2 is implicated in different cancers as a pro-tumor proliferation signal." (PMID 41301006, 2025). "CREB3L2 is also mutated in thyroid carcinomas, where it is fused with peroxisome proliferator-activated receptor γ (PPARγ), a master regulator of fatty acid storage in adipocytes and glucose metabolism in cancer cells, to promote thyroid tumor growth." (PMID 41301006, 2025). "In triple-negative breast cancer, the cleavage of the C-terminal fragment of CREB3L2 does not affect the sonic hedgehog pathway in cancer cells but activates this pathway in infiltrating T cells." (PMID 41301006, 2025).
CREB3L2 also shares sentences with these, for which no sentence is quoted: colon cancer (2 papers); solitary fibrous tumor (2); acute kidney injury (1); brain tumors (1); cervical cancer (1); chondrodysplasia (1); colon adenocarcinoma (1); dermatofibrosarcoma protuberans (1); diabetics (1); diffuse large B-cell lymphoma (1); endometrial stromal sarcoma (1); Ewing sarcoma (1); fibrosarcoma (1); hepatocellular carcinoma (1); infarction (1); infection (1); inflammatory myofibroblastic tumor (1); invasive ductal breast carcinoma (1); Jaundice (1); melanoma (1); metabolic disease (1); myoepitheliomas (1); pancreatic adenocarcinoma (1); proliferative diabetic retinopathy (1); prostate adenocarcinoma (1); skin cancer (1); vitiligo (1).